CRP (C-reactive protein)
Diseases named in the same sentence as CRP in open-access papers (continued):
Sharing a sentence is not in itself a finding about the gene and the disease.
osteomyelitis (continued). "The levels of PCT, ESR, and CRP were measured for all patients and the screening performance characteristics of each marker in predicting the ulcer class, osteomyelitis, and PAD was calculated." (PMID 31555767, 2019). "Elevated serum procalcitonin has been suggested to be a better predictor for the presence of infection or osteomyelitis than the other laboratory markers of inflammation, except CRP." (PMID 28050566, 2016). "In the operative management of pediatric septic arthritis and osteomyelitis, CRP values peak in 1–3 days following surgery, and in uncomplicated cases, normalize within 7–12 days." (PMID 27174186, 2016). "Initial C-reactive protein (CRP), white cell count (WCC) and maximum CRP values in osteomyelitis (OM) and vaso-occlusive crisis (VOC) groups." (PMID 23755165, 2013). "The use of Ultrasound in combination with CRP and WCC is a reliable, cost-effective diagnostic tool for differentiating osteomyelitis from VOC bone infarction in SCD." (PMID 23755165, 2013). "In one study of severe diabetic foot infections, both the leukocyte count and the CRP level were higher in those with exclusively soft-tissue infection than in those with concomitant osteomyelitis." (PMID 24205433, 2013). "There was also a significant difference in mean CRP at presentation for the osteomyelitis group (M = 86.4, SD = 66.2) and VOC group (M = 39.8, SD = 52.4; t = 3.5, p = 0.001, two-tailed)." (PMID 23755165, 2013). "ESR, CRP, white blood cell count, neutrophils and platelet count were higher for patients with acute osteomyelitis than for patients with subacute osteomyelitis." (PMID 18937840, 2008). "The univariable regression analysis showed that age, ulcer duration, CRP, D-Dimer, previous antibiotic therapy, surgical therapy, ulcer type, ulcer size >4cm2, Wanger grade, osteomyelitis, and DKD were significant influencing factors for the occurrence of MDRO infection in DFU patients (P < 0.05)." (PMID 41458536, 2025). "The ESR is usually evaluated with other acute phase reactants with different kinetics (e.g., C-reactive protein, CRP), particularly in the follow-up of patients with osteomyelitis, suspected prosthetic joint infection, and more generally as a prognostic marker of disease course." (PMID 39858246, 2025). "CRP levels ≥25 mg/dL were observed in patients with osteomyelitis or VOC (50%, N=1)." (PMID 39238724, 2024). "In children newly admitted with acute osteomyelitis, a CRP level exceeding 73.23 μg/mL may indicate a high likelihood of MRSA infection." (PMID 39390563, 2024). "The WBC count could be normal, and the ESR and CRP are often elevated; In cases of proven osteomyelitis, those tests may be used to evaluate response to therapy or relapse." (PMID 38975428, 2024). "Other, smaller studies that included less patients than this study, have also shown a positive association between elevated CRP on admission and amputation rates; however, neither of these studies included the presence of osteomyelitis." (PMID 38797920, 2024). "The ESR threshold of 60 mm/h demonstrated a sensitivity of 74% (95% confidence interval [CI], 67–80) and a specificity of 56% (95% CI, 48–63) for osteomyelitis, while the CRP threshold of 7.9 mg/dL had a sensitivity of 49% (95% CI, 41–57) and a specificity of 80% (95% CI, 74–86)." (PMID 39208074, 2024). "CRP levels of 15-19.9 mg/dL were found in patients with osteomyelitis, VOC, or both (33.3%, N=one)." (PMID 39238724, 2024). "This review identified peripheral arterial disease, neuropathy, high Wagner’s grade, osteomyelitis, postprandial glucose level, white cell count, c-reactive protein, erythrocyte sedimentation rate, low hemoglobin, and albumin as the most significant predictors of amputation." (PMID 36035032, 2022).
osteomyelitis (continued). "Receiver operating characteristic curves and the corresponding area under the curve (AUC) values were calculated to evaluate the diagnostic efficacy of such biomarkers commonly used for osteomyelitis as WBCs, ESR, and CRP, as well as the size and number of EVs." (PMID 32793507, 2020). "The area under the ROC curve of CRP in detection of osteomyelitis was 0.67 (95% CI: 0.58-0.76)." (PMID 33134967, 2020). "Area under the ROC curve of CRP in detection of osteomyelitis was 0.67 (95% CI: 0.58-0.76)." (PMID 33134967, 2020). "Two studies have suggested that specific values of ESR and CRP during treatment predict osteomyelitis recurrence; however, this prediction may be misleading because of potential reverse causation." (PMID 31800625, 2019). "Such normalization of CRP values, however, may not indicate bacterial eradication but may simply reflect the fact that the inflammatory response to osteomyelitis is too localized or weak to trigger CRP production from hepatocytes." (PMID 31800625, 2019). "ESR and CRP are important indicators of chronic osteomyelitis in laboratory examination." (PMID 30291260, 2018). "Osteomyelitis was recognized as a possible cause; however, a lack of previous systemic symptoms and the normal values for C-reactive protein and erythrocyte sedimentation rate helped us to rule this out." (PMID 27258509, 2016). "Laboratory values including ESR and CRP are typically elevated in osteomyelitis." (PMID 24516764, 2014). "Although WCC was within normal limits and CRP was only slightly raised at 7.0, in this patient, it is possible that this could have been a case of sub acute osteomyelitis superimposed on an infarct." (PMID 23755165, 2013). "However, acute osteomyelitis exists as a refractory disease even now, which usually exhibits systemic symptoms such as fever, malaise or high levels of CRP and local redness, swelling, or pus discharge." (PMID 24349802, 2013). "However, elevated CRP levels and ESRs found to be consistent among the cases with this condition are relatively sensitive indicators for distinguishing osteomyelitis from bone tumors." (PMID 24148903, 2013). "In this cross-sectional study, serum levels of ESR and CRP were measured for patients with diabetic foot referring to emergency department or endocrinology clinic and the screening performance characteristics of these markers in detection of osteomyelitis were calculated." (PMID 33134967, 2020). "However, other studies suggest that the CRP level may be of prognostic value in patients with acute osteomyelitis or septic arthritis and in differentiating simple from perforated appendicitis." (PMID 22943554, 2012). "Strong correlations existed between NLR, CAR and disease severity markers (CRP, PCT, HbA1c, osteomyelitis, PEDIS stage)." (PMID 41752790, 2026). "Based on the univariable analysis with a significance level of P < 0.1, we included the following 11 variables: age, ulcer duration, previous antibiotic therapy, surgical therapy, ulcer type, ulcer size, Wanger grade, osteomyelitis, DKD, CRP, and D-Dimer." (PMID 41458536, 2025). "The majority of osteomyelitis cases are bacterial in origin, and laboratory findings often reveal elevated erythrocyte sedimentation rate (ESR) and C-reactive protein (CRP) levels." (PMID 41142568, 2025). "Inflammatory markers, such as interleukin-6 (IL-6), tumor necrosis factor-alpha (TNF-α), procalcitonin (PCT), and C-reactive protein (CRP), serve as pivotal indicators in assessing the severity of osteomyelitis." (PMID 40956854, 2025). "WBC, ESR, CRP, and PCT levels are key indicators of inflammation and are crucial for assessing chronic osteomyelitis." (PMID 40951409, 2025). "Patients with chronic osteomyelitis had WBC, CRP, and ESR levels of 6.5 (IQR 5.42–8.01) × 109/L, 6.87 (IQR 3.14–19) mg/L, and 20.5 (IQR 10–47.5) mm/h." (PMID 40951409, 2025).
osteomyelitis (continued). "Osteomyelitis was monitored via routine complete blood count (CBC), comprehensive metabolic panel (CMP), and C-reactive protein (CRP)." (PMID 39258058, 2024). "Patients with a diabetic foot who underwent amputation showed a higher prevalence of osteomyelitis and elevated inflammatory markers, including WBC, ESR, CRP, procalcitonin, and presepsin." (PMID 38673584, 2024). "Exceptions are osteomyelitis (S. suis), intramammary inoculation of E. coli and swine influenza (H1N1), where SAA, haptoglobin (HP) and CRP, pig major acute phase protein (Pig-MAP) and SAA remained unchanged respectively." (PMID 39237955, 2024). "The osteomyelitis diagnosis by using ESR and CRP as biomarkers were also reported by many studies, but the correlation success and cut-off values varied depending on the locations and risk factors." (PMID 37370370, 2023). "Elevated inflammatory markers, such as erythrocyte sedimentation rate (ESR) and C-reactive protein (CRP), are often observed in cases of osteomyelitis." (PMID 38226077, 2023). "Measuring both ESR and CRP may slightly improve sensitivity and negative predictive value for diagnosis; however, further investigation is necessary to establish a certain diagnostic role in osteomyelitis." (PMID 37546085, 2023). "In this study, both CRP and ESR of chronic osteomyelitis patients were observed to continuously and significantly decreased during follow-up periods after surgical treatment." (PMID 37370370, 2023). "In terms of research related to bone infections, these immune-related biomarkers, such as WBCs, CRP, ESR, NLR, MLR, and PLR, are increasingly being evaluated for their abilities of fast and early diagnosis of osteomyelitis and to predict complications." (PMID 35692886, 2022). "In this case, an investigation using magnetic resonance imaging (MRI), elevated levels of erythrocyte sedimentation rate (ESR), C-reactive protein (CRP), and culture was consistent with the diagnosis of osteomyelitis." (PMID 35186571, 2022). "One set of biomarkers of interest are inflammatory biomarkers in DFU osteomyelitis, such as erythrocyte sedimentation rate (ESR) and c-reactive protein (CRP), which was the focus of one recent clinical trial (NCT04025853)." (PMID 34684109, 2021). "In diabetic patients, if the ESR is <30 mm/h, the likelihood of osteomyelitis is low; however, if the ESR is >60 mm/h and the CRP level is >7.9 mg/dL, the likelihood of osteomyelitis is high, and treatment for this should be strongly considered." (PMID 33728350, 2021). "Increased serum inflammatory markers such as White blood cells (WBCs), C-reactive protein (CRP), and erythrocyte sedimentation rate (ESR) have been proposed to aid in diagnosis of osteomyelitis." (PMID 33134967, 2020). "Because the present case did not accept biopsy, we diagnosed acute osteomyelitis pubis by clinically having fever and pelvic pain and elevations in CRP and WBC and demonstrating changes for osteomyelitis in MRI." (PMID 25973280, 2015). "On admission, the median temperature, ESR, CRP, WBC and neutrophils were higher in patients with acute osteomyelitis than in patients with subacute osteomyelitis (p = .007, p = .012, p = .019, p = .008, p = .003 respectively)." (PMID 18937840, 2008). "Normal CRP/WBC does not exclude chronic osteomyelitis; sensitivity is limited once infection is compartmentalized." (PMID 41001299, 2025). "One study ofindividuals with DFU and osteomyelitis found that ESR, WBC count, CRP level, and theCRP/albumin ratio were significantly elevated, whereas the albumin level wasdrastically decreased in patients with osteomyelitis compared to those withoutosteomyelitis." (PMID 40622101, 2025). "Consistent with prior studies, CRP and white blood cell [WBC] counts in our cohort were either mildly elevated or normal at diagnosis, highlighting their limited sensitivity for both diagnosing and monitoring osteomyelitis." (PMID 40005524, 2025).
osteomyelitis (continued). "The duration of onset was longer, and the temperature, white blood cells, neutrophils count, C-reactive protein and D-dimer were less elevated in culture-negative acute osteomyelitis (P < 0.05)." (PMID 39501383, 2024). "Elevated ESR and CRP levels are nonspecific for osteomyelitis because many different inflammatory states will have elevated ESR and CRP levels; a patient with acute osteomyelitis usually has a normal ESR and CRP level, while they can decrease in chronic OM." (PMID 39125464, 2024). "CRP levels of 5-9.9 mg/dL were seen in patients without complications, with osteomyelitis, or with VOC (33.3%, N=one)." (PMID 39238724, 2024). "Baseline CRP was considerably higher in patients treated for osteomyelitis compared to patients not treated for it but not statistically different in patients with probable/confirmed osteomyelitis compared to patients not treated for osteomyelitis." (PMID 39238724, 2024). "Sometimes, in the presence of subclinical osteomyelitis, normal ESR and CRP values can be found." (PMID 39208074, 2024). "ESR rises and drops slower than CRP levels in acute infections and is no longer considered a routine measurement for diagnosing osteomyelitis." (PMID 37546085, 2023). "CRP and ESR are routine inflammatory markers in the evaluation of osteomyelitis." (PMID 35455571, 2022). "Following detailed evaluation of seven articles, the odds ratios of 28 variables were identified, of which nine were acknowledged as the strongest predictors of amputations: elevated WCC, low Hb, low albumin, high CRP and ESR, PAD, neuropathy, osteomyelitis, and Wagner grade >3." (PMID 36035032, 2022). "ESR and CRP are non-specific inflammatory markers used in monitoring various infections such as infective endocarditis and osteomyelitis." (PMID 33557064, 2021). "In contrast, other studies noted procalcitonin was not effective at differentiating uninfected and infected DFUs, with CRP serving as a more sensitive osteomyelitis biomarker instead, though ESR and CRP were noted for being unreliable in the setting of sensory neuropathy." (PMID 34684109, 2021). "High C-reactive protein (CRP), alkaline phosphatase (ALP), periosteal reaction of radiating spicules, and penumbra sign in magnetic resonance imaging (MRI) are helpful for discriminating osteomyelitis from bone tumor." (PMID 33425419, 2020). "Patients with the evidence of osteomyelitis had significantly higher levels of PCT, ESR and CRP." (PMID 31555767, 2019). "Patients with evidence of osteomyelitis had significantly higher level of PCT, ESR and CRP." (PMID 31555767, 2019). "Although the roles of both CRP and ESR in the monitoring of the treatment response for osteomyelitis have been extensively evaluated, it remains unclear which is more appropriate for monitoring the clinical course of PVO." (PMID 31800625, 2019). "Laboratory findings typically show an increase of c-reactive protein (CRP) and erythrocyte sedimentation rate (ESR) especially in acute osteomyelitis in children whilst the white blood count may be normal." (PMID 30039016, 2017). "The factors included a histological type of osteomyelitis, antibiotic therapy before biopsy, fever (temperature ≥38.0°C), elevated WBC count (≥10×103 L), elevated ESR (≥10 mm/h), elevated CRP (≥6 mg/L), the size of the biopsy needle, and the amount of purulent fluid obtained at biopsy." (PMID 24098835, 2013). "ESR and CRP were higher in patients with osteomyelitis than in patients with non-septic arthritis or patients with other conditions (p < .001)." (PMID 18937840, 2008). "Indeed, CRP alone is not always effective in distinguishing between osteomyelitis and degenerative spine diseases." (PMID 39125464, 2024). "Considering that the model in this study needs to differentiate between osteomyelitis and other orthopedic diseases, and that C-reactive protein and erythrocyte sedimentation rate are not essential laboratory parameters for orthopedic diseases, they were not included in this study." (PMID 39568996, 2024).
osteomyelitis (continued). "Whereas the ESR level can vary due to many different factors, including the patient’s gender and age, the CRP level is not affected by any of the known factors, except for the presence and severity of infectious inflammation, such as osteomyelitis and periprosthetic infection." (PMID 36851713, 2023). "believed that the elevated levels of ESR and CRP were not specific for osteomyelitis." (PMID 36686458, 2022). "Persistently elevated or increasing CRP levels which do not follow the expected post-operative trend of peak and decline have been shown to be predictive of infection in adult populations and complications in pediatric osteomyelitis." (PMID 27174186, 2016). "We examined the combined role of ultrasound scan (USS), C - reactive protein and White blood counts (WCC) in aiding early diagnosis in children with SCD presenting acutely with non-specific symptoms such as bone pain, fever or swelling which are common in acute osteomyelitis or VOC." (PMID 23755165, 2013). "In our cases, WBC count was inconsistent with that reported previously, but ESRs and CRP levels were consistent with previous reports indicating high levels are relatively sensitive indicators for distinguishing osteomyelitis from bone tumors, but not from metastatic tumors and Ewing sarcoma." (PMID 24148903, 2013). "Recognition of the risk factors to develop osteomyelitis due to Serratia spp., along with signs of atypical back pain, especially in someone with IVDU, should spur a workup including complete blood count, ESR, CRP, MRI with or without X-ray, as well as blood cultures." (PMID 39314578, 2024). "Although inflammatory markers, including CRP and ESR, are non-specific, they are usually elevated in cases of osteomyelitis." (PMID 41583216, 2025). "C-reactive protein differentiate infectious from non-infectious aetiologies which could prevent unnecessary antibiotic initiation in diseases such as systemic inflammatory response syndrome, respiratory disease, diagnosis of septic arthritis and osteomyelitis and unspecific fever." (PMID 39237955, 2024). "One study found that patients with osteomyelitis who developed DVT had higher inflammatory markers (ESR and CRP) upon admission than those who did not develop DVT." (PMID 39664272, 2024). "Compared with the culture-positive acute osteomyelitis, the duration of onset was longer, and the temperature, WBC, neutrophils count, CRP and D-dimer were less elevated in culture-negative acute osteomyelitis." (PMID 39501383, 2024). "Patients with non-PSD osteomyelitis also showed a higher count of WBC (13,516 vs. 11,167 cells/mm3 of PSD patients, p = 0.022) and increased CRP levels (7.5 vs. 2 mg/dl of PSD patients, p < 0.001)." (PMID 34746055, 2021). "In our case, although it had begun as an acute osteomyelitis, WBC was not remarkable and CRP level increased only slightly, and there was neither pus discharge nor swelling of the cheek until just before the fracture of the mandible." (PMID 24349802, 2013). "In another study leukocyte count, CRP, procalcitonin, and ESR levels were each significantly higher in patients with foot infections, including osteomyelitis, than patients without foot infection." (PMID 24205433, 2013).